PRL (prolactin)
Diseases named in the same sentence as PRL in open-access papers (continued):
Sharing a sentence is not in itself a finding about the gene and the disease.
pituitary adenomas (continued). "Silent lactotroph pituitary adenomas are rare tumors that clinically resemble nonfunctioning macroadenomas but are identified histologically by prolactin immunoreactivity." (PMID 41140514, 2025). "We suggest that, in cases of macroadenomas, normalization of prolactin levels (prolactin levels <26.3ng/mL) after cabergoline administration should be considered a strong predictor of non-functioning pituitary adenomas." (PMID 40960781, 2025). "Baseline characteristics of patients with GH&PRL pituitary adenomas and differences between pretreated and non-pretreated patients." (PMID 40590355, 2025). "For example, a nationwide study from Iceland analyzing 410 cases of pituitary adenomas found that 43% were non-functioning, while 40% were prolactin-secreting." (PMID 40361469, 2025). "Only a few cases of mixed pituitary adenomas secreting prolactin and ACTH have been reported, and none during pregnancy." (PMID 41201503, 2025). "This study aimed to analyze the clinical, hormonal, and radiological characteristics of patients with prolactin (PRL)-secreting PitNETs, also known as pituitary adenomas, treated with DA, in order to identify potential predictive factors of hormonal and radiological response to medical therapy." (PMID 40995599, 2025). "Twenty-five were excluded due to incomplete baseline laboratory levels, one for undergoing surgical treatment, and five because they did not meet the distinct criteria for differentiating between non-functioning pituitary adenoma and PRL." (PMID 38645431, 2024). "In the current study, 75% of patients with nonfunctioning pituitary adenomas confirmed by immunohistochemistry had prolactin levels < 100 ng/dL, with the remaining values ranging from 100 to 250 ng/mL." (PMID 39420933, 2024). "Other hormones such as plasma PRL, GH or FSH and LH may be elevated in patients with pituitary prolactinomas, growth hormone‐secreting pituitary adenomas or gonadotropin‐secreting adenomas respectively." (PMID 39502127, 2024). "On the contrary, PRL-producing pituitary adenomas without elevated PRL were found in a study in 12.1% of pituitary adenomas, and most patients were resistant to dopamine agonist treatment." (PMID 39051300, 2024). "This patient presented a triad consisting of multiglandular PHPT, non-functional GEP, and a pituitary adenoma co-secreting PRL and GH, a type of pituitary tumor common in AIP mutation-positive patients with familial isolated pituitary adenoma." (PMID 37484956, 2023). "The histopathologic report revealed a pituitary adenoma staining positive for GH and negative for prolactin." (PMID 35602875, 2022). "The majority of functional pituitary adenoma (FPA; n = 152) cases were those induced by the overproduction of growth hormone (n = 34; 7.92%) and prolactin (n = 110; 25.64%), followed by those induced by corticotropin (n = 6; 1.40%) or thyrotropin (n = 2; 0.47%)." (PMID 36034373, 2022). "However, the histology and ultrastructure proved that this pituitary adenoma had three distinct cells producing TSH, GH, and PRL." (PMID 36539773, 2022). "Prolactin levels are generally proportional to tumor size and a level greater than 94 ng/ml can differentiate prolactinoma from nonfunctioning pituitary adenoma." (PMID 36337795, 2022). "However, this information is of great importance because GLI1 and SHH are highly expressed by GH-, PRL- and ACTH-expressing human pituitary adenoma, which suggests that HH signaling has an impact on pituitary tumor formation." (PMID 33480359, 2021). "We started CAB at 1 mg/week with a further progressive increase to 3.5 mg/week reaching only a sub-normalization of PRL secretion (27 μg/L) with an absent control of the pituitary adenoma size (13 × 5x11mm)." (PMID 34173929, 2021). "Specifically, 11 patients were affected by pituitary adenomas—6 prolactin-, 2 GH- and 1 ACTH-secreting, and 2 nonfunctioning -, 2 by meningiomas and 1 by craniopharyngioma." (PMID 33200305, 2021).
pituitary adenomas (continued). "Meningiomas (25 cases; 50%) were the most common lesions, followed by pituitary adenomas (22 cases, 44%: 11 PRL-, 3 GH-secreting, and 8 non-functioning), 12 (54.5.%) of which presenting with apoplexy." (PMID 33200305, 2021). "Upregulated in GH-secreting pituitary adenomas with respect to non-functioning pituitary adenomas and prolactin-secreting pituitary adenomas." (PMID 34484116, 2021). "Expression of Dio 2 seems to be variable in pituitary tumors: Dio 2 mRNA levels were increased in different types of pituitary adenoma, including TSH- and PRL-producing adenomas, with unchanged or lower Dio 1/Dio 2 ratios found among patients with similar types of tumors." (PMID 32188093, 2020). "Mainly ACTH-secreting pituitary adenomas were GAL-positive, whereas growth hormone- and prolactin-secreting as well as non-functioning pituitary adenomas showed lower frequencies of GAL-immunoreactivity." (PMID 32265844, 2020). "The proband was diagnosed with functional pituitary adenoma with high serum prolactin in 2010, but the patient did not elect for surgical treatment and was treated with bromocriptine instead." (PMID 29416715, 2018). "2DE, 2DE-based PRL-immunoblot, mass spectrometry, and bioinformatics were used to analyze hPRL variants in human normal (control; n = 8) pituitaries and in five subtypes of pituitary adenomas [NF− (n = 3)-, FSH+ (n = 3)-, LH+ (n = 3)-, FSH+/LH+ (n = 3)-, and PRL+ (n = 3)-adenomas]." (PMID 30210449, 2018). "Migraineurs without pituitary adenomas do not have higher serum PRL levels compared to controls; however, PRL rises during migraine attacks but not tension-type-headaches." (PMID 30356882, 2018). "The patient with Arg9Gln had multiglandular PHPT, non-functioning pancreatic NET and a mixed prolactin and GH-secreting pituitary adenoma." (PMID 29036195, 2017). "The lowest NDRG2 expression was detected in PAs secreting more than one hormone, and the highest in PRL-secreting and non-secreting pituitary adenomas." (PMID 28390436, 2017). "Previous studies have shown that miRNAs are important emerging elements in many types of adenomas, such as GH-secreting, PRL-secreting, and non-functional pituitary adenomas." (PMID 28402262, 2017). "We conclude that PEG inhibits the secretion of GH and PRL in primary cultures of human GH(/PRL)-secreting pituitary adenomas without effect on cell viability or cell proliferation." (PMID 27267119, 2016). "PD-L1 RNA and protein expression were significantly increased in functioning (growth hormone and prolactin-expressing) pituitary adenomas compared to non-functioning (null cell and silent gonadotroph) adenomas." (PMID 27655724, 2016). "Prolactin-secreting pituitary adenomas (nonectopic) are the most common and comprise 48% of all functional adenomas." (PMID 26885420, 2016). "Expression of pSer229-KDR was significantly higher in invasive prolactin pituitary adenomas (mean H-score: 218) than in their noninvasive counterparts (mean H-score: 170)." (PMID 27438154, 2016). "Cushing disease was excluded from these studies for its specificity, for the majority were GH secreting, PRL secreting and non-functioning pituitary adenomas." (PMID 25775019, 2015). "The hormonal types of the patients with pituitary adenoma were nonfunctioning adenoma (n = 22), GH producing adenoma (n = 4), and PRL producing adenoma (n = 1)." (PMID 26339240, 2015). "Preoperative serum prolactin concentrations was 28.4 ± 32.1 and 747.0 ± 1548.9 ng/ml (mean ± SD) in patients with non-functioning pituitary adenoma and prolactinoma, respectively." (PMID 25142896, 2014). "Immunohistochemical analysis of the cells of the pituitary adenoma revealed the following: Positive staining for Syn, and negative staining for GH, LH, PRL, TSH, FSH and ACTH." (PMID 25013498, 2014). "In 212 patients with non-functioning pituitary adenoma, most patients presented between 10 to 20 ng/ml of serum prolactin concentration and the highest prolactin value was 284.9 ng/ml." (PMID 25142896, 2014).
pituitary adenomas (continued). "According to this analysis, cut-off value of serum prolactin concentration to distinguish between non-functioning pituitary adenoma and prolactinoma was 38.6 ng/ml." (PMID 25142896, 2014). "Other reports showed that the serum prolactin values were less than 200 ng/ml in most patients with non-functioning pituitary adenoma." (PMID 25142896, 2014). "The problem still remains to discriminate prolactinoma from non-functioning pituitary adenoma simply with serum prolactin cut-off value." (PMID 25142896, 2014). "So, DAs can normalize the serum prolactin concentration in patients with non-functioning pituitary adenoma, but there is no chance for tumor regression." (PMID 25142896, 2014). "Receiver operating characteristic (ROC) curve analysis was performed, indicating that cut-off value of serum prolactin concentration to distinguish between non-functioning pituitary adenoma and prolactinoma was 38.6 ng/ml." (PMID 25142896, 2014). "Here, we evaluated MVD and the role of VEGF in vascular architecture in 51 pituitary adenomas (24 nonfunctioning, 13 prolactin-secreting, 10 growth hormone-secreting, 3 adrenocorticotropic hormone-secreting, and 1 thyroid-stimulating hormone-secreting)." (PMID 25431591, 2014). "This drug suppresses PRL release in in vitro and in vivo rodent models, and decreases cell viability in non-functioning human pituitary adenomas." (PMID 21464994, 2011). "This pilot study revealed that low-dose (0.25mg) cabergoline could suppress prolactin levels within 48 h in non-functioning pituitary adenomas, helping to discriminate them from prolactinomas." (PMID 40960781, 2025). "Notably, prolactin levels > 250 ng/mL enabled a clear distinction between the etiologies of macroprolactinoma and nonfunctioning pituitary adenoma." (PMID 39420933, 2024). "Therefore, in cases of small, nonfunctioning pituitary adenomas with mildly elevated prolactin levels, the differentiation between microprolactinoma and nonfunctioning incidentaloma is not as clear initially." (PMID 38578472, 2024). "A mild-to-moderate elevation of the prolactin level may occur in non-functioning pituitary adenoma (PA) (NFPA) or in prolactinoma due to the stalk-section effect." (PMID 37057215, 2023). "However, the European Clinical Practice Guidelines on functioning and non-functioning pituitary adenomas in pregnancy recommend not measuring prolactin during pregnancy." (PMID 36013562, 2022). "Moreover, participants with pituitary adenoma had a significantly higher level of prolactin than others, which is not consistent with our study." (PMID 35098010, 2021). "Also, the positive staining of GH and (or) PRL in pure TSH-oma patients was actually understandable because positive IHC staining did not necessarily mean the hypersecretion of hormones, such as silent pituitary adenoma." (PMID 35002961, 2021). "Recently, we also conducted an extensive NMR-based metabolomics study on various immunohistochemical subtypes of pituitary adenomas, and we found that none of these subtypes including the functional pituitary adenomas (PRL/ACTH/LH-FSH and GH secreting) showed the presence of GAGs." (PMID 32033192, 2020). "As a benign tumour derived from the anterior pituitary gland, some pituitary adenomas, like FPA, can induce endocrine disorders by the hypersecretion of hormone, such as adrenocorticotropic hormone (ACTH), thyroid-stimulating hormone (TSH), growth hormone (GH) and prolactin (PRL)." (PMID 31109334, 2019). "Indeed, this step will result in a dramatic rise in PRL levels if the patient has a macroprolactinoma, remaining low in cases of non-functioning pituitary adenomas." (PMID 29768629, 2018). "Finally, the role of p19, encoded by Cdkn2b, as a tumour suppressor in regulating pituitary anterior lobe proliferation has been revealed by a conventional knockout mouse model of Cdkn2b, as Cdkn2b−/− mice developed multiple tumour types including PRL, GH and FSH secreting pituitary adenomas." (PMID 26320859, 2016).
pituitary adenomas (continued). "Since hormone producing cells of the adenohypophysis as well as ACTH-, GH- and PRL-immunopositive adenomas express SHH and its target GLI1, we furthermore propose that excess HH signaling is involved in the development/maintenance of hormone-producing pituitary adenomas." (PMID 27109116, 2016). "However, the sensitivity to develop non-carcinogen induced tumors, like prolactin (PRL)-secreting pituitary adenomas (prolactinomas), in these animals has not been well studied." (PMID 26509893, 2015). "Although recent reports indicated the endocrinological discrimination of non-functioning pituitary adenoma from prolactinoma, the cut-off value of serum prolactin concentration between them varied widely from 94 to 200 ng/ml and there are no definitive diagnostic criteria." (PMID 25142896, 2014). "Thus, once the possibility of the hook effect is excluded, a prolactin value < 100 ng/mL in a patient harboring a solid pituitary macroadenoma virtually excludes a macroprolactinoma and is highly indicative of a nonfunctioning pituitary adenoma." (PMID 39420933, 2024). "Taken together, the serum prolactin cut-off value is not safely applicable to establish a correct diagnosis in patients with large pituitary adenoma, nevertheless tumor size is smaller in prolactinoma than non-functioning pituitary adenoma in general population and border zone patients." (PMID 25142896, 2014). "Among them, 18 reported on non-functioning pituitary adenomas (NFPA), 13 on growth hormone (GH)-secreting adenomas, six on adrenocorticotropic hormone (ACTH)-secreting adenomas, four on prolactin hormone (PRL)-secreting adenomas, and 11 on craniopharyngiomas." (PMID 34638482, 2021). "All pituitary adenomas were resected, with 20 invasive, 34 non-invasive, and 3 not applicable, including 1 ACTH, 6 GH, 1 GH + PRL, 34 NFPA and 7 PRL cases." (PMID 31665029, 2019). "Immunohistochemical stains for growth hormone, prolactin, follicle-stimulating hormone, thyroid-stimulating hormone, luteinizing hormone, and ACTH were negative, revealing a nonfunctional pituitary adenoma." (PMID 23919255, 2013). "In a small percentage of clinically non-functioning pituitary adenomas, positive immunoreactivity to ACTH, growth hormone, prolactin or TSH (singly or combination) are observed." (PMID 22011738, 2011). "Accordingly, they include prolactin-secreting pituitary adenoma (PRLPA), non-secreting pituitary adenoma (NFPA), growth hormone-secreting pituitary adenoma (GHPA), as well as adrenocorticotropic hormone-secreting pituitary adenoma (ACTHPA) and other types of PA." (PMID 36875488, 2023). "In case of secreting pituitary adenomas, overall remission (cure without need for medication) estimates were 45% (95% CI 35–54%) for GH-secreting adenomas, 64% (95% CI 0.52–0.75%) for ACTH-secreting adenomas and 34% (95% CI: 19–48%) for PRL-secreting adenomas." (PMID 34638482, 2021). "Regarding the pituitary adenomas, no pituitary hormonal staining was reported in most patients (i.e., NFPAs; n = 5), while others stained positively for ACTH (n = 2), GH (n = 2), LH (n = 1), and PRL (n = 1)." (PMID 32333269, 2020). "Also protein expressions of Gαi-1, Gαi-2 and Gαi-3 were examined in human GH-, PRL-, ACTH- and non-secreting (NFPA) pituitary adenomas." (PMID 25291362, 2014).
adenoma (308 papers, 2005 to 2026). A neoplasm arising from the epithelium. "The achievement of normal PRL and or adenoma shrinkage equal or more than 50% were significantly associated with remission and independently of the initial PRL level and the initial treatment modality (TSS versus DA)." (PMID 41199869, 2025). "Normalization of serum PRL at 12 months was significantly associated with adenoma shrinkage ≥30% at the same time point (P = 0.01)." (PMID 41178903, 2025). "This difference can most likely be attributed to the extent of cavernous sinus invasion (as higher Knosp grades are associated with a lower likelihood of both complete adenoma removal and prolactin normalization)." (PMID 40035956, 2025). "Conversely, Hispanic ethnicity and functional adenoma, including growth hormone and prolactin-secreting adenomas, were negatively associated with PLOS when defined as > median (p < 0.05)." (PMID 39863778, 2025). "PRL-secreting adenomas can arise due to germline mutations in the case of familial genetic syndromes." (PMID 38370355, 2024). "Thereby, an increased adenoma size (i.e., macroadenoma) is generally associated with elevated serum PRL levels." (PMID 38544490, 2024). "The Klk1 gene was also observed to be associated with prolactin-secreting cells within human Gh1-secreting adenomas." (PMID 35180880, 2022). "In these cases, standard treatment is medical by dopamine agonists (DA), as they cause a rapid decline in serum PRL levels with concurrent reduction in adenoma size." (PMID 36147567, 2022). "The likelihood of remission was associated with a smaller initial adenoma size, lower PRL levels at diagnosis and postpartum, and older maternal age." (PMID 35000899, 2022). "Regarding mutations in the AIP gene, patients with these mutations inactivating the AIP gene generally have adenomas that produce GH and/or prolactin." (PMID 31365626, 2019). "One patient had F-MEN1 (multiglandular PHPT and non-functioning pancreatic NET) and three S-MEN1 (two with uniglandular PHPT associated with a prolactin-secreting adenoma, and one with multiglandular PHPT associated with a glucagonoma)." (PMID 29036195, 2017). "Larger adenomas cause higher PRL levels and elevated concentrations are found in up to 17% of such cases." (PMID 28593164, 2017). "Prolactin-secreting adenomas which mainly express sst1 and sst5, often associated with D2R, show low sensitivity to somatostatinergic treatment that scarcely reduces prolactin secretion." (PMID 23476673, 2013). "Nonetheless, our results are more in-line with more recent findings showing that GH-secreting adenomas are more often associated with diabetes than GH- and PRL-secreting ones." (PMID 24039977, 2013). "In this study, we present a young male patient with a pituitary macroadenoma showing cytoplasmic immunoreactivity to prolactin in association with dense and diffuse lymphocytic infiltration within the adenoma tissue and his follow-up course." (PMID 22011738, 2011). "The AIP mutation-positive patients who clinically presented with a nonfunctioning adenoma all had positive GH and/or PRL staining in the adenoma tissue, suggesting that all subjects with AIP mutations have GH or PRL-synthesizing adenomas in our cohort." (PMID 20506337, 2010). "Lower baseline PRL and smaller adenoma size were associated with better clinical improvement." (PMID 41178903, 2025). "Since ERT may cause a decrease in the efficacy of DA, the evaluation of PRL secretion before and after the start of replacement therapy and the careful measurement of adenoma size by MRI over the first year are warranted, while continuing DA therapy." (PMID 35000899, 2022). "Therefore, the SF3B1R625H mutation appears to be a unique genetic signature of PRL-secreting adenomas." (PMID 32427851, 2020).